VCAM1 (vascular cell adhesion molecule 1)
Diseases named in the same sentence as VCAM1 in open-access papers (continued):
Sharing a sentence is not in itself a finding about the gene and the disease.
diabetic nephropathy (22 papers, 2009 to 2024). "Serum adiponectin concentration was previously reported to be positively associated with soluble vCAM-1 level and was associated with the ED measured by the flow-mediated dilatation in type 2 DM patients with diabetic nephropathy." (PMID 37626670, 2023). "Even though an increase in the level of cell adhesion molecules (ICAM-1 and VCAM-1) and selectins (E-selectin, P-selectin and L-selectin) were found during the development of diabetic nephropathy, a significant association was observed with baseline levels of VCAM-1, P-selectin and L-selectin only." (PMID 36843591, 2023). "Furthermore, a recent paper identified P-selectin and VCAM-1, as well as interleukin 18, as markers pathogenetically linked to, and predictive of diabetic nephropathy." (PMID 31906326, 2020). "Potential prospects for use in pathology and treatment include elevated levels of vascular cell adhesion molecule 1 (VCAM-1) and neprilysin in patients with baseline diabetic nephropathy and diabetic nephropathy-treated patients with persisting albuminuria, respectively." (PMID 38389064, 2024). "For diabetic nephropathy, VCAM-1, P-selectin and L-selectin were found to be significantly associated with microvascular complications (OR=0.996, 95%CI=0.995-0.998, p=<0.001, OR=0.995, 95%CI=0.989-1.0, p=0.050, and OR=1.0, 95%CI=1.00-1.002, p=0.008, respectively)." (PMID 36843591, 2023). "Moreover, LINC00968, which is co-expressed with ENG and VCAM1, can promote the proliferation and migration of endothelial cells and accelerate the proliferation and fibrosis in diabetic nephropathy." (PMID 33790949, 2021). "VCAM-1 has also been reported to predict poor long-term outcome in other patient groups at risk of CVD, that is, in hemodialysis patients, in patients with diabetic nephropathy and in patients with manifest CAD." (PMID 20003285, 2009). "The patients with advanced diabetic nephropathy had a significantly higher proportion of PT_VCAM1 compared to control or early diabetic nephropathy patients, suggesting that PT_VCAM1 and tubular injury may be related to disease progression in diabetic nephropathy." (PMID 33850129, 2021). "In diabetic nephropathy, it significantly reduces NF-κB and TGF-β levels, while in left ventricular hypertrophy, benazepril reduces TGF-β, VCAM-1, and NF-κB expression, and ROI’s production." (PMID 35163696, 2022). "Reduction in:-TNF-α production;-NF-κB and TGF-β levels in diabetic nephropathy;-TGF-β, VCAM-1, and NF-κB expression, and ROI’s production;-left ventricular hypertrophy and fibrosis." (PMID 35163696, 2022). "It is reported that ICAM-1, VCAM-1, and MCP-1 play important roles in the pathogenesis of diabetic nephropathy through inducing inflammatory cell infiltration." (PMID 24260158, 2013). "From recent studies using several animal models such as glomerulonephritis, unilateral ureteral obstruction, diabetic nephropathy and 5/6 nephrectomy, the expressions of MCP-1, VCAM-1 and osteopontin have been shown to be elevated." (PMID 19633031, 2011). "Nrf2/HO-1 axis activation and subsequent attenuation of oxidative stress strongly suppressed inflammation and downregulated intercellular adhesion molecule 1 (ICAM-1), vascular cell adhesion molecule 1 (VCAM-1), and inflammatory nitric oxide synthase (iNOS) in a mouse model of diabetic nephropathy." (PMID 36818747, 2023). "Consistent with our studies, there is no direct evidence thus far that the blockade of VCAM-1 by antibodies or deletion of the genes ameliorating the progression of diabetic nephropathy in animal models." (PMID 25303153, 2014).
heart failure (22 papers, 2017 to 2025). Inability of the heart to pump blood at an adequate rate to meet tissue metabolic requirements. "For example, vascular cell adhesion molecule 1 (VCAM-1) expression in the myocardium is closely associated with immune cell infiltration and increased risk of heart failure." (PMID 37568452, 2023). "VCAM1 can promote the production of ROS and promote the occurrence of heart failure by activating matrix metalloproteinase to cause ventricular remodeling." (PMID 35811741, 2022). "VCAM1 can promote the differentiation and infiltration of immune cells, which is positively correlated with the risk of heart failure and promote the development of heart failure." (PMID 35811741, 2022). "Even more, VCAM-1 has been proposed as a reference molecule for diagnosis of viral myocarditis and is used to identify subjects at risk for events related to heart failure." (PMID 29416512, 2018). "We found that higher serum VCAM-1 levels indicated a lower possibility of heart failure, which contradicted the findings of previous studies." (PMID 39049003, 2024). "Our results indicated that VCAM-1 levels were increased in the serum of patients with heart failure (HF) and the hearts of Ang II-infused mice." (PMID 36467095, 2022). "FOXO1 is an important transcription factor, which can promote the promotion of transcription and affect the occurrence and development of heart failure by directly acting on the promoter regions of VCAM1 and intercellular adhesion molecule-1 (ICAM1)." (PMID 35811741, 2022). "Injection of human VCAM1-expressing CFs (VCFs) in postinfarct heart failure rat models (ligation of the left anterior descending artery) led to a significant restoration of the left ventricle contraction." (PMID 32936824, 2020). "Therefore, we evaluated the circulating biomarkers GDF-15, H-FABP, suPAR, and VCAM-1 in a single center cohort of advanced heart failure patients clinically presenting in the chronic and acute forms, thus aiming to show their sensitivity to HF decompensation." (PMID 39598008, 2024). "Moreover, increased expression of ICAM-1 and VCAM-1 was observed in heart failure patients." (PMID 35734399, 2022). "Visfatin increase in type-2 DM patients was related to heart failure and acute coronary syndromes; visfatin appears to mediate vascular endothelial inflammation by inducing the expression of adhesion molecules (VCAM-1 and ICAM-1) and pro-inflammatory cytokines such as IL-1β, IL-6, and TNF-α." (PMID 28590452, 2017). "The nomogram-histogram also indicated an effect of prosaposin on respiratory failure, whereas VCAM-1 and NGAL were predicted factors for postoperative heart failure and coagulation dysfunction, respectively." (PMID 39049003, 2024). "We found elevated levels of the circulating biomarkers suPAR, GDF-15, VCAM-1, and H-FABP in patients with heart failure." (PMID 39598008, 2024). "ROS are implicated in the pathogenesis of various cardiac disorders, including MI and heart failure, and can promote the expression of endothelial adhesion molecules, such as ICAM-1 and VCAM-1, that are critical for neutrophil recruitment." (PMID 35113814, 2022). "To further elucidate the specific mechanisms through which LA and ALA improve heart failure symptoms, we conducted exploration testing on several candidate pathways provided in the literature, including inflammatory response (TNF-α, VCAM-1) and vasodilation (VEGF)." (PMID 41154077, 2025).
Hypercholesterolemia (22 papers, 2010 to 2024). An increased concentration of cholesterol in the blood. "VCAM-1 levels were reduced in both groups, being only significant in the hypercholesterolemia group (p < 0.05) with a 12.5% decrease." (PMID 37513556, 2023). "Hypercholesterolemia results in an increased expression of VCAM-1 by endothelial cells during atheroma formation: in line with this observation, Nbs targeting VCAM-1 have been used for the in vivo detection of atherosclerotic lesions." (PMID 33353213, 2020). "The endothelial migration is mainly mediated by cellular adhesion molecules such as vascular-cell adhesion molecule 1 (VCAM-1), which is typically up-regulated in response to hypercholesterolemia." (PMID 30935055, 2019). "We propose other mechanisms of endothelial dysfunction, inflammatory markers and vascular adhesion molecule (VCAM-1) regulation by hypercholesterolemia and its treatments." (PMID 28985743, 2017). "Hypercholesterolemia leads to endothelial expression of adhesion molecules such as vascular cell adhesion molecule-1 (VCAM-1) at atheroprone areas such as curvatures and bifurcations." (PMID 26702331, 2015). "In the settings of hypercholesterolemia, VCAM-1 is upregulated at atheroprone areas in ApoE−/−mice in association with plasma cholesterol." (PMID 26702331, 2015). "In this concern, administration of FFM ameliorated the elevated cholesterol, LDL, homocysteine, and VCAM1 in HCD-induced hypercholesterolemia, this effect may be due to the active ingredient of FFM via correcting the imbalance in the measured markers." (PMID 28985743, 2017). "Soluble CSF VCAM1 and ICAM1 levels, which reflect changes in the endothelial layer of the BBB, have been correlated with CNS inflammatory changes, while in the periphery, VCAM1, and ICAM1 are upregulated in hypercholesterolemia and associated with early atherogenic lesions." (PMID 36927447, 2023). "Decreased levels observed of endothelial adhesion molecules, VCAM-1 and ICAM-1, may indicate a better prognosis for complications of hypercholesterolemia." (PMID 37513556, 2023). "Hypercholesterolemia effectively promotes VCAM-1 expression without evident stimulation of inflammation." (PMID 20856927, 2010).
hyperlipidemia (21 papers, 2010 to 2025). "The Vcam1 gene is normally up regulated by hyperlipidemia and by inflammatory cytokines, proposing a potentially higher inflammatory condition in the chicken fed mice." (PMID 26839578, 2016). "To further elucidate the effect of hyperlipidemia on VCAM-1 expression, we compared expression levels in wt and ApoE−/− mice fed regular chow or high fat diet (HFD), this time at an earlier age of 17 weeks." (PMID 20856927, 2010). "The in vitro chip model results showed great consistency with the in vivo model's data, which demonstrated that the antioxidant property of platinum-NPs that scavenged hyperlipidemia induced ROS in ECs in vitro and decreased the expression of vascular cell adhesion protein 1 (VCAM-1) in vivo." (PMID 35155603, 2021). "When non-diabetic mice of different genotypes were compared, ApoE−/− mice were found to express higher VCAM-1 levels than wt mice (p<0.05), suggesting that hyperlipidemia may induce VCAM-1 expression in retinal vessels." (PMID 20856927, 2010). "In the case of hyperlipidemia-induced oxidative stress and inflammation of heart, aloe-emodin significantly reduced the expression levels of proinflammatory cytokines (IL-1β, IL-6, and TNFα), as well as vascular cell adhesion molecule 1 (VCAM1) and intercellular adhesion molecule 1 (ICAM-1)." (PMID 35744949, 2022). "In high-fat-diet-induced rat hyperlipidemia, lycopene restored the level of TJ molecule claudin-5, and decreased VEGF, vascular cell adhesion molecule-1 (VCAM-1) and proinflammatory cytokines." (PMID 40077636, 2025). "Interestingly, TNFα and IL-1β have also been shown to induce VCAM-1 expression by this pathway and may account in the absence of hyperlipidemia but under hyperglycemic conditions (such as in the diabetic wt mice in this study), for the observed up-regulation of VCAM-1 in retinal vessels." (PMID 20856927, 2010). "Although hyperlipidemia and disturbed blood flow can also promote NFκB activation and expression of inflammatory cytokines and leukocyte adhesion molecules, endothelial cell VE‐PTP deletion in ApoE−/−/VE‐PTPiECKO mice was not accompanied by changes in ICAM1 or VCAM1 in aortic endothelial cells." (PMID 36740996, 2023).
osteosarcoma (21 papers, 2019 to 2025). A usually aggressive malignant bone-forming mesenchymal neoplasm, predominantly affecting adolescents and young adults. "miR-95-3P was previously reported as a diagnostic and prognostic marker for osteosarcoma, and is also upregulated in cervical carcinoma where it promotes tumor development by regulating VCAM-1." (PMID 38827810, 2024). "Exogenous IGFBP-3 is also known to promote cell migration by upregulating transcription of the gene that encodes vascular cell adhesion molecule 1 (VCAM-1) in osteosarcoma cells." (PMID 35798794, 2022). "Evidence demonstrates that VCAM-1 advocated cascade relevance for tumorigenesis and metastasis and may be associated with the survival of osteosarcoma metastatic cells." (PMID 34760697, 2021). "CXCL1 and CXCL13 are able to induce VCAM-1 expression in osteosarcoma cells through the NF-kB pathway, which in turns favors VCAM-1 dependent migration of cells." (PMID 40071851, 2025). "The screening of candidate targets in NGF-treated osteosarcomas revealed that the NGF-induced upregulation of VCAM-1 was more pronounced than that of ICAM-1 or CCL2." (PMID 39247831, 2024). "Transfecting osteosarcoma cells with FAK or c-Src siRNA was also shown to reduce VCAM-1 synthesis and monocyte adhesion." (PMID 39247831, 2024). "NGF also enhanced VCAM-1-dependent monocyte adhesion within the osteosarcoma microenvironment by down-regulating miR-513c-5p levels through the FAK and c-Src cascades." (PMID 39247831, 2024). "This was the first study to demonstrate a correlation between the miR-513c-5p/VCAM-1 axis and macrophages in osteosarcoma." (PMID 39247831, 2024). "Osteosarcoma cells transfected with VCAM-1 siRNA were shown to antagonize VCAM-1 expression and moderate NGF-induced monocyte adhesion, which indicates that NGF augments VCAM-1-dependent monocyte adhesion to osteosarcoma." (PMID 39247831, 2024). "In the current study, we determined that NGF facilitates VCAM-1-dependent monocyte adhesion and M2 polarization in the osteosarcoma microenvironment." (PMID 39247831, 2024). "Stimulating osteosarcoma cells with an FAK inhibitor or c-Src inhibitor (PP2) eliminated VCAM-1 synthesis, monocyte adhesion, and CD206 expression." (PMID 39247831, 2024). "In summary, this study demonstrated that NGF augments VCAM-1-dependent monocyte adhesion within the osteosarcoma microenvironment and facilitates M2 macrophage polarization by inhibiting miR-513c-5p expression via the FAK and c-Src signaling cascades." (PMID 39247831, 2024). "In the current study, we obtained in vitro and in vivo evidence of NGF facilitating VCAM-1-dependent monocyte adhesion and M2 macrophage polarization in the osteosarcoma microenvironment." (PMID 39247831, 2024). "The expression of VCAM1, a classical adhesion molecule, was used to evaluate the vessel state of the osteosarcoma tissue." (PMID 36405691, 2022). "Another study showed that IGFBP-3 induced the expression of VCAM-1 and mediates the migration of human osteosarcoma cells through the activation of PI3K, Akt, and AP-1 signaling pathways." (PMID 36713521, 2022). "The correlated expression of CXCL1 and VCAM-1 was observed in the immunohistochemistry staining from human osteosarcoma specimens." (PMID 34760697, 2021). "IGFBP-3, an essential regulator of IGF-1 signaling, was shown to facilitate VCAM-1 expression that promoted human osteosarcoma cell migration capacity through the PI3K, Akt, and AP-1 signaling pathways." (PMID 34069554, 2021). "Inhibitors of FAK (FAKi), PI3K (LY294002 and wortmannin), Akt (Akti), and NF-κB (TPCK and PDTC) were applied and showed a clear suppression pattern of CXCL1-triggered cell migration and VCAM-1 mRNA expression in MG63 osteosarcoma cells." (PMID 34760697, 2021).
osteosarcoma (continued). "The IHC results revealed higher levels of CXCL1 and VCAM-1 expression in patients with a higher-grade osteosarcoma than in those with a lower-grade osteosarcoma; the levels of CXCL1 and VCAM-1 expression were reflected by the tumor stage (–C)." (PMID 34760697, 2021). "A positive correlation observed between the CXCL1 and VCAM-1 staining intensity of the human osteosarcoma tissue (r2 = 0.562) indicated that the levels of these proteins were associated with the progression of osteosarcoma." (PMID 34760697, 2021). "Our results suggested that CXCL1 via the CXCR2/FAK/PI3K/Akt/NF-κB pathway enhanced VCAM-1 expression to assist the migratory and invasive activity in osteosarcoma cells." (PMID 34760697, 2021). "The PLCβ, PKCα, and c-Src signaling pathways appear to play a role in CXCL13-facilitated VCAM-1-dependent osteosarcoma cell migration." (PMID 32847038, 2020). "In osteosarcoma, levels of VCAM-1 expression correlate with disease stage and tumor progression, with higher levels of VCAM-1 expression enabling connective tissue growth factor to stimulate the migration of osteosarcoma cells and promote metastasis." (PMID 32847038, 2020). "VCAM-1 expression levels in osteosarcoma cells were dramatically increased after treatment with HPAECs CM." (PMID 32079335, 2020). "Our study identified that CXCL13/CXCR5 axis facilitate VCAM-1 production and cell migration in human osteosarcoma via the phospholipase C beta (PLCβ), protein kinase C α (PKCα), c-Src, and nuclear factor-κB (NF-κB) signaling pathways." (PMID 32847038, 2020). "Pretreatment with pathway inhibitors (FAKi, LY294002, Wortmannin, Akti, TPCK, and PDTC) clearly inhibited cell migration and VCAM-1 expression in osteosarcoma cells." (PMID 32079335, 2020). "High levels of CXCL1 secreted by human pulmonary artery endothelial cells (HPAECs) promoted osteosarcoma cell mobility, which was mediated by the upregulation of VCAM-1 expression." (PMID 32079335, 2020). "Our study has identified that the CXCL13/CXCR5 axis facilitates VCAM-1 production and the migration of human osteosarcoma cells via the PLCβ, PKCα, c-Src, and NF-κB signaling pathways." (PMID 32847038, 2020). "In this study, we found that CXCL13 facilitates PLCβ, PKCβ, and c-Src phosphorylation, while PLCβ, PKCα, and c-Src inhibitors reduce CXCL13-induced stimulation of VCAM-1 production and osteosarcoma cell migration." (PMID 32847038, 2020). "Here, we found that CXCR5 siRNA and CXCR5 antibody markedly inhibited CXCL13-induced VCAM-1 expression and cell migration, suggesting that the CXCL13/CXCR5 interaction regulates VCAM-1-mediated migration of human osteosarcoma cells." (PMID 32847038, 2020). "We hypothesize that diminishing VCAM-1 synthesis is a logical therapeutic strategy aimed at limiting osteosarcoma growth." (PMID 39247831, 2024). "In osteosarcoma, VCAM-1 expression is correlated with tumor formation and disease stage 16." (PMID 39247831, 2024). "In addition, PI3K and Akt inhibitors caused a massive reduction in connective tissue growth factor (CTGF)-induced VCAM-1 expression in osteosarcoma cells." (PMID 39768198, 2024). "Results showed that the expression of VCAM1 in primary osteosarcoma patients was significantly higher than that in recurrent osteosarcoma patients, which suggested that a better vessel state may be related to a better outcome." (PMID 36405691, 2022). "Additionally, DHTS has been shown to impair the migration of osteosarcoma cells (143B) by downregulating cell adhesion markers like VCAM-1 and ICAM-1." (PMID 34319041, 2021). "Overexpression of VCAM-1 could occur in the metastatic cancer cells and correlated with the stage of disease including tumor progression in osteosarcoma enhancing the connective tissue growth factor stimulation to promote migration and metastasis." (PMID 34760697, 2021).